ARF6 (ARF GTPase 6)
Diseases named in the same sentence as ARF6 in open-access papers (continued):
Sharing a sentence is not in itself a finding about the gene and the disease.
tumor (continued). "Knockdown of loner, but not steppke, suppressed RasV12 tumour overgrowth, mimicking the effect of blocking the function of spi or Egfr or Arf6." (PMID 28281543, 2017). "Specific IGF2BP3-bound transcripts—ARF6 and ARHGEF4—that are preferentially translated in membrane protrusions induce further formation of membrane protrusions; consequently, IGF2BP3 promotes cell invasiveness and tumor metastasis." (PMID 25216519, 2014). "For each tumor derived from control-RNAi S2-013 cells, cytoplasmic IGF2BP3-containing granules were less abundant in the central region than in the penumbra of the tumor; moreover, ARF6 mainly localized in the cytoplasm of these cancer cells." (PMID 25216519, 2014). "By comparison, transport of miRNAs into microvesicles is less well defined, but experiments involving tumor cell derived microvesicles suggests that miRNA and pre-miRNA translocation is mediated by the interaction of the small GTPase ADP-ribosylation factor 6 (ARF6) and Exportin-5." (PMID 39376631, 2024). "With clinicopathological features analysis of HCC patients, we found that high level of ARF6 expression obviously correlated with poor tumor differentiation (P = 0.014), incomplete tumor encapsulation (P = 0.005), advanced tumor TNM stage (P = 0.001), and tumor recurrence (P = 0.006)." (PMID 37716993, 2023). "A detailed investigation will be required on how activation of the ARF6-based pathway affects the number and function of immune cells in the TME and their response to various immunotherapies, and consequently how the ARF6-based pathway modulates anti-tumor immunity." (PMID 37834383, 2023). "Studies on drugs targeting ARF6 and its upstream or downstream molecules have demonstrated that the eIF4A inhibitor silvestrol, which blocks the translation of ARF6 mRNA, and the MVP inhibitor statin, which blocks ARF6 activity, inhibit ARF6-based tumor malignancy." (PMID 37834383, 2023). "However, the role of ADAP1 in tumorigenesis and its contribution to ARF6-mediated tumor progression had not previously been evaluated." (PMID 31792062, 2019). "However, to date, no Arf6 inhibitors blocking the invasion of tumour cells have been reported." (PMID 33673086, 2021). "Although other ARF6 GAPs and guanine nucleotide-exchanging factors (GEFs) might also regulate the potential laminin internalization, these results indicate that ADAP1 promotes invasive migration of TGF-β-responding tumor cells by facilitating the breakdown of the BM." (PMID 31792062, 2019). "To further evaluate the correlation between ARF6 and lncRNA MDFIC-7 expression, we examined the expression of ARF6 mRNA and lncRNA MDFIC-7 in tumor and adjacent non-tumor tissues by RT-qPCR." (PMID 34621682, 2021). "Consistent with the PtenWT tumor cell lines, tumors from Ptenf/f; Arf6f/f mice showed increased levels of pro-apoptotic proteins BAK and BIM, suggesting enhanced apoptosis signaling in the absence of ARF6." (PMID 40909781, 2025). "Intra-tumor heterogeneity may exist in HCC, which seemed to be reflected by the non-uniform expression of the Arf6 and ARNO, even within the same cancerous lesion." (PMID 31752956, 2019).
cancer (93 papers, 2009 to 2026). A tumor composed of atypical neoplastic, often pleomorphic cells that invade other tissues. "Mounting evidence has linked aberrant ARF6 activation to different perspectives of cancer advancement encompassing the capacity to migrate, invade, and metastasize." (PMID 40275490, 2025). "ARF6 has been associated with several cell-surface receptors expressed on cancer cells, such as CD147, CD44, CD98, CD55, and CD59." (PMID 40733075, 2025). "While the prevalence of Ras in many cancers (e.g., through mutations, for instance) has been recognized for many years, ARF6 and/or its regulators has also been shown to be upregulated in some cancers." (PMID 34344896, 2021). "ARF1 and ARF6 are well characterized as crucial regulators for vesicular trafficking, and their roles have been implicated in the cancer progression." (PMID 27517156, 2016). "ARFs are a family of Ras-related GTP binding proteins, ARF6, in particular, is implicated in cancer invasion and metastasis." (PMID 26185744, 2015). "By controlling recycling of lipids and proteins in the endocytic pathway, ARF6 has been implicated in several cell polarization events including cell migration and cancer invasion." (PMID 25799492, 2015). "ARF6 is associated with the progress of cancer invasion and metastasis." (PMID 37716993, 2023). "It is partly reported about underlying signaling pathways in ARF6-induced cancer progression." (PMID 37716993, 2023). "ARF6 is also believed to be implicated in the glycolysis of cancer cells." (PMID 35899235, 2022). "Furthermore, a spliced variant of ARF6 guanine nucleotide exchange factor was found to regulate the cancer cell migration and invasion." (PMID 31636653, 2019). "We reasoned that mitochondrial aggregation caused by blockade of the Arf6-based pathway might also induce RIRR-like phenomena in single cancer cells." (PMID 29992963, 2018). "In addition, Arf6 is implicated in cell shape and motility during cancer invasion and wound healing through the regulation of surface E-cadherin expression." (PMID 27622210, 2016). "Since loss of functional AJ is regarded as a hallmark of EMT and cancer cell invasiveness, Arf6 may function as a critical determinant of cell-cell AJ disassembly and cancer cell EMT." (PMID 25779663, 2015). "Thus, KRAS mutations appear to cause the overexpression of MYC and ARF6 proteins in cancer cells." (PMID 37158894, 2023). "In this context, our findings suggest that cancer cells activate ARF6 in a positive feedback loop to maintain BRAFV600E protein expression during kinase inhibition." (PMID 40909781, 2025). "While its siblings, such as ARF1 and ARF5, have been widely investigated for their contributions to intracellular trafficking and organelle function, ARF6 has quietly been making waves in the field of cancer research." (PMID 40275490, 2025). "Our work significantly expands the understanding of ARF6's functions in cancer and lays the foundation for future investigations into the translational potential of ARF6 and its downstream effectors as biomarkers or therapeutic targets in AML." (PMID 40275490, 2025). "Previous studies indicated that epidermal growth factor (EGF) receptor (EGFR) induces GEFs to activate ARF6 in invasive cancers, which promotes cancer cell migration and invasion." (PMID 40082743, 2025). "Although Arf6 is essential for cell polarization, Arf6 hyperactivity can promote invasiveness and metastatic activity of cancer cells by increasing their motility." (PMID 40075218, 2025). "Given that ARF6 can regulate both PI3K-AKT8 and BRAFV600E -MAPK signaling and apoptosis upon serum withdrawal, we asked if ARF6 supports the viability of BRAF-mutant human cancer cells grown in full serum." (PMID 40909781, 2025). "Recent studies have indicated that ADP‐ribosylation factor 6 (ARF6) is overexpressed across various cancer types; however, its specific role and implications in AML have yet to be thoroughly investigated." (PMID 40275490, 2025).
cancer (continued). "ACAP4, an ADP-ribosylation factor 6 (ARF6) GTPase-activating protein, was first identified in HCC tissues and was implicated in carcinoma cell movement and invasion through interaction with ARF6 14,26,27." (PMID 39744421, 2025). "ARF6 has been extensively studied in cancer and it is known to regulate cancer cell growth, angiogenesis, invasion, and the formation of metastases." (PMID 38533085, 2024). "ARF6 regulates cancer progression by activating cell movement and invasion, and can promote the cell biological behavior of prostate cancer and liver cancer." (PMID 38617932, 2024). "In line with this, statins, which are inhibitors of MHG-CoA reductase of the MVP and hence inhibit the production of geranyl–geranyl pyrophosphate, block ARF6 activation and inhibit cancer malignancy." (PMID 37158894, 2023). "Mutations in the KRAS gene, and protein overexpression of c-MYC (referred to as MYC) and ARF6 are frequent in many types of cancers." (PMID 37158894, 2023). "The ARFGEF inhibitor SecinH3 and the ARF6 inhibitor NAV-2729 have potential for cancer therapy, as they enhance vascular permeability and have shown efficacy in various animal pathological models." (PMID 37834383, 2023). "Here discussed are that KRAS, MYC, and ARF6 are biochemically and functionally closely related with each other in promoting cancer malignancy and immune evasion." (PMID 37158894, 2023). "Mutations in the KRAS gene and overexpression of protein products of the MYC and ARF6 genes occur frequently in cancer." (PMID 37158894, 2023). "Arap3, a dual GTPase-activating protein (GAP) for the small GTPases Arf6 and RhoA, plays key roles in regulating a wide range of biological processes, including cancer cell invasion and metastasis." (PMID 36674645, 2023). "The end result of this cooperation appears to be the promotion of ARF6-based cancer invasion, metastasis, acidosis, radioresistance, and immune evasion, accompanied with increased mitochondrial activity." (PMID 37158894, 2023). "Here I discussed the mutually inseparable relationships and cooperation of KRAS, MYC, and ARF6 in cancer malignancy and immune evasion." (PMID 37158894, 2023). "Overexpression of the ARF6 protein is frequently seen in various types of cancers, including those of the pancreas, breast, kidney, lung, and head and neck, to be statistically correlated with poor patient survival." (PMID 37158894, 2023). "It is interesting to note that elevated levels of activated Arf6 have been reported to exist in a number of dysfunctional situations such as cancer cells." (PMID 36902414, 2023). "Here, we show that the scaffold protein CNK2 promotes cancer cell migration by coupling the pro-metastatic receptor tyrosine kinase AXL to downstream activation of ARF6 GTPase." (PMID 37322019, 2023). "The alternations in ARF6 mRNA expression in EAC was explored further by separating the expression data by the grade of cancer." (PMID 35143561, 2022). "In this report, we, therefore, analysed the expression of ARF6 at the mRNA level from cancers and corresponding healthy controls from 17 different tissues." (PMID 35143561, 2022). "In this report, we analysed the expression of ARF6 mRNA in cancers and corresponding healthy controls from 17 different tissues by real-time qualitative polymerase chain reaction (RT-qPCR)." (PMID 35143561, 2022). "ARF6 mRNA expression is further increased in higher cancer grades II and III (average of 62- and 67-fold increase) showing statistical significance of p = 0.0197 and p = 0.0403, respectively." (PMID 35143561, 2022). "Further assessments should be done to validate and expand the differential expression of ARF6 in healthy and cancer tissues." (PMID 35143561, 2022). "We found that the Arf-GTPase ARF6, and its downstream effector AMAP1 (also called ASAP1/DDEF1), are often overexpressed in various types of cancer, including PDAC, and closely associated with poor patient survival." (PMID 36408139, 2022).
cancer (continued). "In this study, we showed differential expression of ARF6 mRNA in 17 different cancer tissues with a particular focus on EAC–given a significant upregulation of ARF6 in this cancer." (PMID 35143561, 2022). "Although the expression of ARF6 in some cancers has been investigated previously, this is the first time a widespread array of cancer tissues has been used to investigate the expression of this gene." (PMID 35143561, 2022). "Overall, we showed that ARF6 expression is upregulated during EAC cancer progression, highlighting this small GTPase as a potential biomarker for EAC." (PMID 35143561, 2022). "In summary, among the ARF family of small GTPases, ARF6 is uniquely involved in many cancer types and sub-types." (PMID 35143561, 2022). "In this report, a more widespread analysis of ARF6 gene expression in healthy and cancer tissues was sought using the Origene’s TissueScan Cancer Survey cDNA array (381 samples covering 17 different cancers)." (PMID 35143561, 2022). "Arf6 and its regulators, arguably involved in cancer progression, are promising drug targets for cancer therapy." (PMID 33673086, 2021). "Here, we report the identification and the characterization of chlortetracycline (CTC) as a potent chemical inhibitor of Arf6 activity and Arf6-dependent cancer cell invasion in vitro." (PMID 33673086, 2021). "As part of the RAS family, ADP ribosylation factor 6 (ARF6) regulates the invasion, metastasis and proliferation of cancer cells, and is closely related to autophagy and immunity." (PMID 34503532, 2021). "Mechanistically, the ARF6-AMAP1 pathway drives cancer cell invasion and immune evasion, via upregulating β1-integrins and PD-L1, and downregulating E-cadherin, upon ARF6 activation by external ligands." (PMID 34001163, 2021). "GIT1, which inactivates ARF6 specifically, is highly expressed in several types of cancers, including breast, cervical, colon and liver." (PMID 32426352, 2020). "By regulating the delivery of β1 integrin back to the plasma membrane via recycling endosomes, Arf6 coordinates cell adhesion, migration, and cancer cell invasion." (PMID 32322163, 2020). "Overexpression of Arf6 or of its regulators in cancer cells suggests an important role in cell adhesion, migration, and invasive behaviour." (PMID 32322163, 2020). "Owing to this activity, cancer cells overexpressing the ARF6 pathway demonstrate robust resistance against ionizing radiation." (PMID 32580737, 2020). "Regarding the ARF GEFs, BRAG2/GEP100 and EFA6, which activate ARF6 specifically, are known to be involved in cancer progression." (PMID 32426352, 2020). "Significantly, in vivo mouse studies have shown that expression of constitutively active Arf6 can promote invasion of cancer cells into healthy tissue." (PMID 33186390, 2020). "Our data also show for the first time the role of the ARF6–PLD-1 axis in NK cell-mediated ADCC of cancer cells." (PMID 30647406, 2019). "It has essential roles in cell division, cell migration, cell spreading, cell polarity, and adhesion, and aberrant Arf6 activation is found in metastasis and cancer cell invasion." (PMID 31060328, 2019). "Consistent with the previous studies showing that the ARF6-CA mutant suppresses the invasive activity of cancer cell lines, forced expression of the ARF6-CA mutant in ADAP1-overexpressing cells reduced the invasive activity, whereas ARF6-WT did not affect." (PMID 31792062, 2019). "The Arf6 pathway appears to drive the epithelial-mesenchymal transition (EMT) of cancer cells; this pathway downregulates E-cadherin and upregulates integrin recycling and focal adhesion dynamics, when AMAP1 binds to PRKD2 and EPB41L5." (PMID 29329590, 2018). "Consistent with this, blocking Egfr or Arf6 suppresses Hh signalling and inhibits the growth of either fly or human cancer cells harbouring oncogenic Ras." (PMID 28281543, 2017). "Knockdown of Arf6 in flies or human cancer cells suppresses the overgrowth of cell harbouring oncogenic Ras." (PMID 28281543, 2017).
cancer (continued). "Taken together, we conclude that Arf6 regulates Hh signalling in both flies and human cancer cells to control growth." (PMID 28281543, 2017). "These considerations led us to investigate the relationship between the small GTPases Ral and Arf6 in adhesion-dependent signalling in normal cells and anchorage-independent signalling in Ras transformed cancer cells." (PMID 27269287, 2016). "ARF6 is often overexpressed in many types of cancer and facilitates epithelial-mesenchymal transition and invasiveness." (PMID 27517156, 2016). "We therefore examined the role of RalA and RalB in regulating Arf6 in K-Ras expressing pancreatic (MiaPaCa2) and H-Ras expressing bladder (T24) cancer cells." (PMID 27269287, 2016). "This study hence identifies Arf6, through this regulatory crosstalk, to be a key downstream mediator of Ral isoform function along adhesion dependent pathways in normal and cancer cells." (PMID 27269287, 2016). "It does however raise the question if this difference in how Arf6 is regulated in these two cell lines is conserved across other H-Ras and K-Ras dependent cancers." (PMID 27269287, 2016). "ARF6 has been shown to be over-expressed in cancer cells with higher protein levels correlating with a highly invasive nature." (PMID 26185744, 2015). "Immunohistochemical analysis using a commercial antibody to ARF6 showed a significant increase in the observed sum of staining intensity (protein expression) and distribution between cancer and matched normal samples (P = 0.047)." (PMID 26185744, 2015). "It is notable that many of the molecules and processes identified in this study, including SFKs, Arf6, and differential integrin expression and recycling, play a fundamental role in both wound healing and cancer invasion." (PMID 23453597, 2013). "Our results indicated that Arf6 plays an essential role in cancer cell migration during EGF stimulation." (PMID 22701712, 2012). "GEP100, one of the guanine nucleotide exchanging factors (GEFs) for Arf6, has been implicated in EGF signaling and cancer invasion." (PMID 22701712, 2012). "We have previously shown that EGFR, when tyrosine-phosphorylated, binds to GEP100/BRAG2 to activate Arf6, which induces cancer invasion and metastasis." (PMID 21966491, 2011). "Here we show that overexpressed Her2 activates another small GTPase, Arf6, via its association with GEP100, and induces cancer cell invasion." (PMID 21966491, 2011). "In this article, we discuss Arf6 signaling in cancer invasion and metastasis, together with the molecular mechanisms by which this Arf6 pathway functions." (PMID 19416474, 2009). "Likewise, Arf6 activation leads to the phosphorylation of myosin light chain and actomyosin contraction, which allows the vesicles to bud off from the membranes of cancer cells." (PMID 41348103, 2026). "This ARF6-dependent mechanism may be exploited in BRAFV600E driven cancers as a therapeutic vulnerability." (PMID 42050077, 2026). "Collectively, these findings elucidate an ARF6-dependent mechanism of BRAF oncoprotein synthesis that may be exploited in BRAFV600E driven cancers as a therapeutic vulnerability." (PMID 40909781, 2025). "Interestingly, EGF-activated Akt induces the phosphorylation of Acapin at its Ser247 residue (AcapinS247), which promotes ARF6 GTPase activity for powering cancer cell migration." (PMID 40082743, 2025). "The upregulated expression of ARF6 may therefore result in increased exocytosis of membrane-type matrix metalloproteinases, consistent with promoting cancer cell invasion." (PMID 39217195, 2024). "ARFs family (ARF1, ARF3, ARF4, ARF5, ARF6) are generally highly expressed in Pan-cancer." (PMID 38617932, 2024). "Interestingly, human CNK2 and the HYP homolog SAMD12 have recently been shown to control cancer cell migration by mediating ARF6 activation induced by AXL signaling." (PMID 38388830, 2024).